CD44 (CD44 molecule (IN blood group))
Diseases named in the same sentence as CD44 in open-access papers (continued):
Sharing a sentence is not in itself a finding about the gene and the disease.
breast carcinoma (continued). "CTC subsets were selected for EpCAM negativity but positivity for CD44+/CD24− stem cell signature; along with combinatorial expression of uPAR and int β1, two markers directly implicated in breast cancer dormancy mechanisms." (PMID 26631983, 2015). "CD44 is a molecule highly expressed by breast cancer cells, which promotes invasion and adhesion to BM." (PMID 26064994, 2015). "In this study, we aimed to investigate the role of CD44 activation states in targeting therapy to breast cancer cells." (PMID 25909172, 2015). "Accordingly, CD24 in combination with CD44 is currently considered as a marker for cancer stem cells in breast cancer." (PMID 26444008, 2015). "To further validate the idea GO was reducing stemness in MCF7-derived CSCs, we used a series of well-established breast cancer stem cell markers (CD44 and CD24), and quantitatively analyzed their expression by FACS analysis." (PMID 25708684, 2015). "TGF-β1 acted on MDA-MB231 breast cancer cells by decreasing cell proliferation, changing cell morphology to a fibroblast-like shape, increasing expressions for CD44 and GSN, and increasing EMT expression and cell migration/invasion." (PMID 26482896, 2015). "The CD44+/CD24− immunophenotype has been successfully used as a biomarker to identify cancer stem-like cells in breast cancer cell populations." (PMID 25919570, 2015). "In particular, a CD44+/CD24−/low subpopulation was identified to have tumour-initiating properties in breast cancer, and its tumourigenic phenotype was demonstrated to be related to stem cell-like properties." (PMID 26444008, 2015). "It is also reported that the higher expression of SRp40 correlates with alternative pre-mRNA splicing of CD44; suggesting the possibility of the SNP, rs8192431, to be used as a marker for breast cancer." (PMID 25768091, 2015). "In breast cancer, the CD44+/CD24− subpopulation, which refers to breast cancer stem-like cells, showed enriched metastatic abilities in a xenograft model." (PMID 25919570, 2015). "Under the condition of 2 ng/ml TGF-β1 for 3 days, the population of CD44+/CD24- MDA-MB231 breast cancer cells were increased." (PMID 26482896, 2015). "In breast cancer cells, CD44 has been shown to stimulate the guanine exchange activity of p115RhoGEF leading to activation of RhoA, a GTPase involved in cytoskeletal organization and adhesion." (PMID 25886367, 2015). "Luteolin suppressed progestin-mediated increases in stem cell-like properties of breast cancer cells in established assays examining CD44 expression, mammosphere formation, and ALDHbright activity." (PMID 26312209, 2015). "Sphere culture is currently the most common method for enriching a CD44+CD24−/low breast cancer cell population by 40–98% from clinical specimens or cell lines." (PMID 26305906, 2015). "Together, high levels of CD44 expressed by CSCs and breast cancer cells are significantly correlated with BCLM." (PMID 25885919, 2015). "In breast cancer cells, the activation of YB-1 at serine 102 mediates resistance to trastuzumab by increasing the number of CD44-positive cells." (PMID 25790262, 2015). "A study in MDA-MB-468 breast cancer cells has shown that CD44 cross-linking and signaling upon HA binding activates c-Jun nuclear translocation." (PMID 25954275, 2015). "Specially, we focused on the function of the CD44 intracellular domain (CD44ICD) with regards to breast cancer stemness." (PMID 25909162, 2015). "The role of CD44 in breast cancer was abundantly described in literature, in particular its duality in cancer progression." (PMID 26504780, 2015). "Although only one-third of human breast cancers have the CD44+/CD24− phenotype, this tumor cell population appears most commonly in TNBC." (PMID 25429827, 2015). "Most notably, CD44 is a common marker of CSCs in several types of human carcinoma, including cancers of the breast, prostate, bladder, colon, ovary, stomach, cervix, uterus, nasopharynx, head and neck, lung, and pancreas." (PMID 26322272, 2015).
breast carcinoma (continued). "Breast cancer stem-like cell (BCSC) populations have recently been identified based on the cell membrane markers CD44+/CD24-/ ESA+ cells." (PMID 26338199, 2015). "Its expression correlates with the expression of a stem cell marker CD44 in breast carcinomas and its targeting results in the inhibition of breast cancer stem cell expansion in hypoxia." (PMID 24409151, 2014). "Whereas some tumors such as gliomas exclusively express CD44s, other neoplasms including gastrointestinal cancer, bladder cancer, uterine cervical cancer, breast cancer, and HNSCC also express CD44 variants." (PMID 24122205, 2014). "In this study, we developed DNA aptamer that bind to CD44 exon v10 and demonstrated the potential role for CD44-EphA2 complex to promote breast cancer migration." (PMID 24586375, 2014). "Metformin has been reported to enhance trastuzumab efficacy in animal model by killing CD44+/CD24− breast cancer stem cells." (PMID 24457597, 2014). "CD44–hyaluronan interactions have been suggested to take place in the lipid rafts of breast cancer cells to facilitate oncogenic signalling, while CD44 interactions with the cytoplasmic binding partner merlin have been shown to inhibit cancer cell growth." (PMID 24512624, 2014). "The EMT signatures included a signature seen in CD44(hi)/CD24(lo/-) enriched breast cancer stem cells and an EMT core signature produced by overexpression of Twist, Snail, Gsc and TGF-β1." (PMID 25519510, 2014). "The cell surface markers CD44 and CD24 are adhesion molecules and CD44+CD24− cells were suggested to be breast cancer stem cells." (PMID 24363201, 2014). "The first identification of CSCs in solid tumors was made in 2003, when CSCs were identified and isolated from breast cancers using CD44 and CD24 markers." (PMID 24528676, 2014). "This novel HA/CD44-mediated c-Jun signaling pathway and miR-21 production provide a new drug target for the future intervention strategies to treat breast cancer." (PMID 24606718, 2014). "Cancer stem/progenitor cell populations have been isolated in clinical samples of breast cancer tissue that characteristically show a CD44+/CD24–/lin− phenotype and also preferentially express other stem cell markers such as nucleostemin and active ALDH-1." (PMID 25209720, 2014). "Although CSCs have been isolated and identified in many somatic cancers, only a few somatic CSC markers, such as CD44+/CD24−/low for breast cancer, have been extensively accepted." (PMID 24489842, 2014). "Qualitative and quantitative changes in expression of CD44 and its isoforms have been demonstrated for several tumor models revealing prognostic significance for neuroblastoma, breast cancer, squamous cell esophageal cancer, osteosarcoma, and gastric cancer." (PMID 24491153, 2014). "In summary, our observations support the notion that the interaction between CD44 and hyaluronan regulates microvascular endothelial cell tubulogenesis by affecting the expression of cytokines and their receptors, as well as breast cancer dissemination." (PMID 24614402, 2014). "Molecularly, miR-34a suppresses breast cancer invasion and metastasis by directly targeting Fra-1 and inhibits the metastasis of osteosarcoma cells by repressing the expression of CD44." (PMID 24528540, 2014). "The objective of the current study was to further characterize the roles of LSR and CD44 during C. perfringens iota cytotoxicity on breast cancer cells." (PMID 24990559, 2014). "This notion was consistent with the recent studies demonstrating that cultured human breast cancer cells shows heterogeneity of the expression of various isoforms of CD44." (PMID 24586375, 2014). "Previously, we showed that the extracellular domains of EphA2 and CD44 can be displayed on the yeast cell surface and used to identify mAbs from a phage antibody library pre-selected on breast cancer cells overexpressing EphA2 and CD44." (PMID 25353955, 2014).
breast carcinoma (continued). "In this study we employed the luminal ER+ MCF-7 and the IBC SUM149PT breast cancer cells to establish the extent to which high grade of CIN and chemoresistance was mechanistically linked to the enrichment of CD44+/CD24low/− CSCs." (PMID 24970653, 2014). "In fact, this current study reveals that CD44 prevents endocytosis of iota toxin and conveys cytotoxic resistance in breast cancer cells." (PMID 24990559, 2014). "Given the fact that EphA2 regulates tumor cell migration and invasion, our results suggest that it forms a molecular complex with CD44 through exon v10 and this promotes TN breast cancer migration." (PMID 24586375, 2014). "The predominant expression of CD44 by microvascular endothelial cells prompted us to investigate its involvement in breast cancer transient adhesion to endothelium as the first step during their dissemination." (PMID 24614402, 2014). "Chronic exposure to cigarette smoke causes the emergence of cell populations bearing markers of self-renewing stem-like cells in breast cancer, including CD44+ cells." (PMID 24971320, 2014). "CD44 has also been identified as one of the well-known markers of breast-cancer-initiating cells (BCICs)." (PMID 24971320, 2014). "Previous studies indicated that HA/CD44-mediated oncogenic signaling plays an important role in the development of several solid tumors including breast cancer." (PMID 24606718, 2014). "Another group has demonstrated that the JAK2/STAT3 signaling was specifically required for the growth of CD44+/CD24− stem cell-like breast cancer cells in human tumors." (PMID 24297508, 2014). "No obvious changes in morphology and cell size and CD44 staining pattern were observed in breast cancer cells treated with Bay-11-7082." (PMID 25184276, 2014). "In this study, we characterized CD44+CD24- breast CSC from a human breast cancer cell line, BT-20 cells, and found that CSC had potent capacity to form mammospheres in vitro and solid tumors in SCID mice, consistent with previous studies." (PMID 25301732, 2014). "CD44+/CD24- have been identified as cancer stem cell markers for breast cancer, CD133+ aimed at brain tumors and colon cancer, as well as CD20 designed for melanoma." (PMID 24670249, 2014). "Breast cancer is the first human carcinoma in which a subpopulation of cells displaying a specific CD44+/CD24-/low/ESA+ antigenic phenotype was found to have TIC properties." (PMID 25216750, 2014). "In breast cancer, cells with CD44+/CD24−/low/epithelial cell adhesion molecule (EpCAM)+ phenotype were identified as the cancer stem cells." (PMID 25229616, 2014). "Claudin-low tumors express decreased levels of CDH1, are enriched for EMT markers, and are CD24 low/CD44 high, which are features of self-renewing breast cancer stem cells." (PMID 25252859, 2014). "Others have shown that high CD44 expression correlates to a basal-like phenotype and unfavorable prognosis in breast cancer patients." (PMID 24990559, 2014). "Previous study indicated that autophagy positively regulates the CD44+CD24-/low breast cancer stem-like phenotype; however in the present study our data showed that resveratrol-induced autophagy plays a negative mechanism for BCSCs maintenance." (PMID 25068516, 2014). "The MDA-MB-231 and MDA-MB-231-BM breast cancer cell lines, which express high amounts of CD44 and are surrounded by hyaluronan containing pericellular matrices, were studied." (PMID 24614402, 2014). "Our data are consistent with a novel model whereby palmitoylation-induced retention of CD44 within lipid rafts exerts a suppressive effect on breast cancer cell migration." (PMID 24512624, 2014). "CD44+/CD24-/low is considered to be the biomarker for the tumor stem/progenitor cell phenotype in breast cancers." (PMID 25213022, 2014). "In particular, magnetic nanoclusters were modified with HA (HA-MNCs) in a study aimed at detecting CD44 + breast cancer by magnetic resonance imaging." (PMID 24642908, 2014).
breast carcinoma (continued). "Clarke and colleagues isolated TICs from metastatic human breast cancers based on their specific CD44+/CD24-/low/ESA+ antigenic phenotype." (PMID 25216750, 2014). "Several studies have found CD44 to have a role in impaired prognosis in many malignant tumors, such as hepatic carcinoma, lung carcinoma, breast carcinoma, melanoma, gastric carcinoma, and HNSCC." (PMID 24122205, 2014). "In breast carcinomas, a cell population with the phenotype CD44+CD24−/low has been shown to be enriched for tumourigenic stem/progenitor cells." (PMID 24178749, 2014). "We, therefore, performed a matrigel invasion assay to determine the effect of CD44 down-regulation by NF-κB inhibition on the metastatic potential of breast cancer cells." (PMID 25184276, 2014). "To determine the effect of NF-κB inhibition induced CD44 repression on breast cancer cell properties, we first examined cell morphology (e.g., size and CD44 staining pattern) after Bay-11-7082 treatment to determine if the cells were healthy after treatment." (PMID 25184276, 2014). "Our findings in this study, thus, established a direct correlation with NF-κB inhibition and CD44 repression in breast cancer cells, and provide new insight in the molecular mechanism of CD44 regulation." (PMID 25184276, 2014). "It has also been reported that basal-like tumors contain the highest percentage of CD44-positive cells, while high CD44 expression correlates to a basal-like phenotype, increased metastases, and unfavorable prognosis in breast cancer patients." (PMID 24990559, 2014). "In recent years, the up-regulation of CD44 has served as a marker for tumor initiating cells in breast cancer and other cancer types." (PMID 25184276, 2014). "It is know that administration of neoadjuvant chemotherapy to breast cancer patients increases the fraction of CD44+/CD24−/low tumor cells." (PMID 24632568, 2014). "We then classified all samples according to a GES of breast cancer stem cells (CD44+/CD24-/low-mammospheres-forming cells)." (PMID 25277734, 2014). "Although hyaluronan has previously been used to stimulate CD44-dependent migration, in this study we concentrated on ligand-independent breast cancer cell migration induced via scratch-wounding." (PMID 24512624, 2014). "We present novel evidence that CD44 palmitoylation is temporally reduced during breast cancer cell migration." (PMID 24512624, 2014). "MMP9 can be localized to the surface of murine mammary carcinoma cells via the hyaluronan receptor CD44, as a component of tumor cell invadopodia structures, where it can facilitate invasion and angiogenesis by proteolytic activation of latent TGF-β." (PMID 24811362, 2014). "Both NIPBC-1 and NIPBC-2 cell lines showed the presence of 0.2% and 0.1% of CD44+/CD24- breast cancer stem cells respectively which is relatively similar to the commercially available breast cancer cell line." (PMID 24502646, 2014). "CD44 is a family of cell-surface glycoproteins that are expressed in a variety of tissues, including breast cancer tissues." (PMID 24606718, 2014). "Hyaluronan binding to CD44 affects the adhesiveness of breast cancer cells, but also converts signals via CD44 resulting in regulation of gene expression such as the expression of chemokine genes." (PMID 24614402, 2014). "CD44+ cells are proposed to be cancer stem cells (CSCs) because CD44 is a well-known marker of breast-cancer-initiating cells (BCICs)." (PMID 24699672, 2014). "In breast cancer, these cancer stem cells are enriched as a subpopulation of cells with CD44+/CD24−/low phenotype and form tumors in animals with as few as 100 cells." (PMID 25229616, 2014). "In the present study, we investigated the role of LSR and CD44 in a tissue-specific manner by identifying which protein mediates the cytotoxic processes specific to breast cancer." (PMID 24990559, 2014).
breast carcinoma (continued). "pRb has been implicated as an important factor in regulating neuronal cell migration and was recently found to inhibit CD44 induced collective cell migration of breast cancer cells." (PMID 25568667, 2014). "Given the fact that EphA2 plays a key role in promoting tumor invasion and metastasis, our results suggest a novel model of a molecular complex consisting of CD44 and EphA2 that facilitates TN breast cancer progression." (PMID 24586375, 2014). "We demonstrate that LSR is the cell-surface protein that mediates iota toxin cytotoxicity through endocytosis in breast cancer cells, and propose a novel role for CD44 as a driver of resistance towards iota toxin via inhibition of endocytotic mechanisms." (PMID 24990559, 2014). "Breast cancer cell lines (MDA-MB-231, MDA-MB-468, MCF7 and T47D) and primary human breast cancer cells were labelled with pre-conjugated with fluorescently antibodies to CD44, CD24 and ESA (stem cell markers), 7-AAD (viability marker) and Hoechst (Cell cycle)." (PMID 25277201, 2014). "Breast cancer stem cells (CSCs) isolated from the tumors were determined by flow cytometry analysis using CD44+/CD24- or low." (PMID 24914410, 2014). "HA-MNCs exhibited superior biocompatibility and excellent properties for the targeted diagnosis of CD44-overexpressing breast cancer in vitro and in vivo." (PMID 24642908, 2014). "This concept was extended to solid tumors by Clarke and Wicha, who demonstrated that human breast cancer contains a subpopulation of cells with stem-like properties bearing the surface markers CD44+/CD24−/lin−." (PMID 24489842, 2014). "To determine if CD44 exon v10 was involved in tumor cell migration, we tested anti-CD44 v10 antibody for its ability to inhibit migration of triple-negative (TN) breast cancer cells, HCC38." (PMID 24586375, 2014). "Collectively, these results suggest a novel clinical relevance for the regulation of palmitoylation and lipid raft affiliation of CD44 in breast cancer cells." (PMID 24512624, 2014). "Our observation that CD44 repression results in decreased invasiveness and migration in breast cancer cells is consistent with the notion that CD44 expression is one of the key determinants of the migration and invasiveness of cancer cells." (PMID 25184276, 2014). "Further investigation indicated that the IL-6/JAK2/STAT3 pathway was preferentially active in CD44+CD24− breast cancer stem cells, and inhibition of JAK2 decreased the number of cancer stem cell number and blocked the growth of xenografts in mice." (PMID 24995504, 2014). "For example, the CD44+CD24lo/2 breast CSCs are enriched in breast cancer patients who have received adjuvant chemotherapy and more resistant to some chemotherapeutic drugs." (PMID 24423412, 2014). "Breast cancer cell lines known to express the target antigens ErbB2, EphA2, EphB3, and CD44 with high and low levels were stained with the identified phage mAbs and evaluated by fluorescence microscopy." (PMID 25353955, 2014). "CD44 repression via NF-κB inhibition consequently decreased proliferation and invasiveness of breast cancer cells." (PMID 25184276, 2014). "In this study, we employed the luminal ER+ MCF-7 and the IBC SUM149PT breast cancer cell lines to establish the extent to which high grade of CIN and chemoresistance were mechanistically linked to the enrichment of CD44+/CD24low/− CSCs." (PMID 24970653, 2014). "Characterization of CD44+CD24-Cancer stem cell(CSC) derived from breast cancer cells indicated that CSC rapidly formed mammospheres and had potent tumorigenicity in vivo." (PMID 25301732, 2014). "Then, we tuned the aggregated parameters using the biological constrains, described in Material and Methods, combined with the experimental values of breast cancer volumes and the proportion of CSCs derived from the percentage of Sca-1+ and CD44+/CD24− cells." (PMID 25184361, 2014).